IRF4 (interferon regulatory factor 4)
Diseases named in the same sentence as IRF4 in open-access papers (continued):
Sharing a sentence is not in itself a finding about the gene and the disease.
tumor (continued). "Deletion of IRF4 in Treg cells resulted in enhanced antitumor immunity and delayed tumor growth in a mouse model of cancer." (PMID 33748292, 2021). "Here, we found that the expression of IRF4 was decreased in the MDSCs treated with supernatant from tumor cells compared with the supernatant from 3T3 cell." (PMID 33708218, 2021). "Specifically, IRF3, IRF7, and IRF9 were significantly upregulated in tumor tissues, whereas IRF4 was downregulated (P < 0.001)." (PMID 34488791, 2021). "IRF4 was severely down-regulated in the tumor tissues of Model group as compared with the normal colon tissues." (PMID 33468159, 2021). "In vitro cell culture showed that the expression of IRF4 in MDSCs induced by the supernatant of cultured tumor cells was significantly decreased compared with the MDSCs induced by the supernatant of cultured 3T3 cells (P<0.05)." (PMID 33708218, 2021). "Despite the extensive studies on the roles of IRF4 in tumor biology, the function in tumor immunology remains poorly understood." (PMID 33708218, 2021). "Using UALCAN database, we identified that IRF4 expression was significantly higher in LUAD tumor compared to normal samples both at the transcriptional and protein levels (P < 0.001 and P < 0.001)." (PMID 34195096, 2021). "Our analysis confirmed a positive correlation between IRF4 expression and favorable patient outcome, thus validating our findings that IRF4 plays a tumor suppressor role in BC." (PMID 32855526, 2020). "Three weeks after orthotopic tumor induction, tumor weight of Irf4−/− mice was significantly increased compared to IRF4 sufficient Irf4flox/flox controls." (PMID 32448983, 2020). "In contrast, IRF4 deletion in LysM+ cells increased tumor weight and led to moderately expanded M-MDSC population in the spleen; yet there was no impact on survival." (PMID 32448983, 2020). "IRF4 has also been found to have both oncogenic and tumor suppressive activities in hematological cancer." (PMID 32855526, 2020). "In contrast, myeloid cell-specific deletion of IRF4 in LysMCreIrf4fl/fl mice slightly accelerates tumor growth, which was accompanied by increased M-MDSC frequency in the spleen." (PMID 32448983, 2020). "The B-cell specific TF POU2F2 was predicted to inhibit tumor cell apoptosis and enhance transcription, and IRF4 in combination with ATF6 was predicted to play an important role in the development of hematopoietic neoplasm." (PMID 32585984, 2020). "Upstream regulatory analysis implicated increased activation of STAT1 and IRF1, and inhibition of Interferon-stimulated transcription mediated by IRF4, in hot tumours." (PMID 30104673, 2018). "Differently from other hematologic malignancies, this miRNA displays tumor suppressor activities in MM, affecting growth and survival, impairing the expression of IRF4 and its downstream targets." (PMID 27903272, 2016). "Another tumor suppressor miRNA downregulated in MM is miR-125b-5p, which has been shown to target interferon regulatory factor 4 (IRF4), a lymphocyte-specific transcription factor with an oncogenic role in MM." (PMID 26881223, 2016). "We conclude that separating the ABC-DLBCL subset according to relative expression of the two IRF4 cofactors SPIB and BATF identifies subgroups differentially linked to previously defined features of DLBCL tumour biology." (PMID 24875472, 2014). "IRF4, a member of the interferon regulatory factor (IRF) family, is implicated in the survival of tumour cells." (PMID 24510125, 2014). "In this report, we provide evidence that IRF4 functions as a tumor suppressor in c-Myc induced B cell leukemia." (PMID 21818355, 2011). "In addition, expression of IRF4 in the tumor immune environment is suppressed during development of MDSCs, as well as during tumor formation." (PMID 40858576, 2025). "Accumulating evidence indicates that IRF4 governs anti-tumor T cell immunity." (PMID 40733503, 2025).
tumor (continued). "Long-term pursuits on these studies could lead to novel therapeutic strategies by targeting the IRF4 regulatory network to enhance anti-tumor immunity and improve patient outcomes." (PMID 40733503, 2025). "We used IHC to stain the IRF4 protein of tissue and tumor slides." (PMID 40607252, 2025). "However, in ccRCC, CXCL13-CXCR5 interactions paradoxically promote tumor proliferation and migration 100, aligning with our observation that reducing IRF4 lowers pro-tumorigenic CXCL13." (PMID 40607252, 2025). "Impressively, hIRF4‐ASOs significantly reduced tumour volume and lowered IRF4 mRNA levels." (PMID 40356256, 2025). "Functionally, IRF4 knockdown in ccRCC cells resulted in diminished proliferation, invasion, and migration alongside increased apoptosis, suggesting that IRF4 exerts a pro-tumorigenic effect and impedes the development of a mature, anti-tumor immune microenvironment." (PMID 40607252, 2025). "Previous studies have elucidated IRF4's involvement across various tumor types." (PMID 40607252, 2025). "Strategies to restore miR-125a-5p function or inhibit IRF4 could potentially counteract arsenic-induced immunosuppression and hinder tumor development." (PMID 41301548, 2025). "SCRIPro could accurately predicts well-known master regulators including SPI1, IRF1, FLI1, and STAT2 for mono/macrophages, GATA3, RUNX3, SMARCA4, JUND, and MYB for T-cells, PAX5, BCL2, and IRF4 for B and tumor B-cells." (PMID 39024032, 2024). "Blocking IRF4 could be a potential therapeutic strategy to reinvigorate exhausted T cells and enhance anti-tumor immunity." (PMID 39149248, 2024). "The expressions of AP-1, IRF4, Zeb1, and TGFβ in 4T1 tumor tissue are presented in Supp." (PMID 38355711, 2024). "However, the regression analysis only showed a significant correlation between tumor volume and tumor growth rate as well as IRF4 and CD68 mRNA levels with growth rate having the strongest influence on tumor volume." (PMID 39272860, 2024). "Furthermore, another TF, interferon regulatory factor 4 (IRF4), is strongly associated with the anti-inflammatory and immunosuppressive M2 macrophage (CD163+) phenotype that supports tumor growth." (PMID 37380989, 2023). "Besides, the relationship between abundance of tumor-infiltrating lymphocytes (TILs) and expression, copy number and methylation of IRF4 in pan-cancer was analyzed through TISIDB." (PMID 36797470, 2023). "IRF4 indicated significant prognostic values and could be potential therapeutic biomarkers in targeting tumor immunity of OSCC51." (PMID 36797470, 2023). "Moreover, we found that RAB13 silencing enhanced the expression of interferon regulatory factors-1 (IRF1) and IRF4, which are vital factors mediating tumor immunity." (PMID 36901767, 2023). "However, IRF4 expression is decreased in immature myeloid cells, such as MDSCs in tumor-bearing mice and chronic myeloid leukemia cells." (PMID 36814912, 2023). "Additionally, we observed that IRF4-driven tumor cells exhibited several important malignant features." (PMID 35504924, 2022). "Notably, IRF4 also regulates many genes that are specifically expressed in and characterize each tumor type." (PMID 36077849, 2022). "In addition, IRF4-dependent cDC2s were found to promote the growth of MC38 tumor cells and to inhibit the infiltration of Th1 and TNF-α–producing cells into the tumor." (PMID 35454882, 2022). "First, the exhaustion of CD8+ cells is a common cause of the failure of immunotherapy, and the cooperation of BATF with IRF4 could counter this exhaustion in tumor-infiltrating CAR T-cells." (PMID 35573731, 2022). "We first demonstrated in DLBCL that IRF4 can upregulate the PD-L1 expression of tumor cells." (PMID 35983077, 2022). "However, the function of IRF4 in tumor immunology is still poorly understood compared with the extensive studies on IRF4 in tumor biology." (PMID 33708218, 2021).
tumor (continued). "However, further research investigating the associations of IRF4 rs12203592, CCND1 rs1485993, TERT rs2242652, and MX2 rs45430 with underlying biologic pathways related to tumor progression is warranted." (PMID 34898573, 2021). "It suggested that the elevated levels of PMN-MDSC in the IRF4 KO mice could be a secondary effect of the increased tumor progress." (PMID 33708218, 2021). "In addition, to detect the role of IRF4 in tumor growth, B16 tumor cells were injected into the WT and IRF4 KO mice subcutaneously." (PMID 33708218, 2021). "Above all, high IRF4 expression might be reflect a state having predominantly tumor-specific TILs which play an important role in tumor control and prevent tumor progression." (PMID 34195096, 2021). "It implied that there might be some Prostaglandin E2 in the supernatant of cultured tumor cells which decreased the expression of IRF4 in MDSCs." (PMID 33708218, 2021). "Simultaneously, a difference in tumor metastasis was detected in WT and IRF4 KO tumor-bearing mice." (PMID 33708218, 2021). "These tumor prone macrophages could express the transcription factor IRF4, which promoted CD8+ T cell exhaustion and acts as an up-regulator of PD-1 expression." (PMID 32756500, 2020). "Due to the increased PMN- and M-MDSC frequency in IRF4 knockout mice, we hypothesized that a MDSC-intrinsic role of IRF4 might explain the effect on tumor progression." (PMID 32448983, 2020). "We have shown that the combinatorial drug therapy induces a new anti-tumor mechanism involving promoter demethylation of IRF4, a previously unknown tumor suppressor gene in this context." (PMID 32855526, 2020). "Furthermore, this tumor-promoting function was demonstrated in mice with tamoxifen-induced ablation of Irf4 in Treg cells, which display reduced growth of transplanted colon adenocarcinoma." (PMID 33143070, 2020). "More recently, it was shown that IRF4 expression also defines the activated subset of tumor-infiltrating Treg cells in patients with lung cancer and may even regulate the human aTreg phenotype." (PMID 33143070, 2020). "While our work shows that IRF4 silencing indeed promotes tumor growth, further studies will be needed to fully decipher the exact anti-tumor program driven by IRF4 in BC, as well as the signaling pathways controlling its expression in both normal and BC tissues." (PMID 32855526, 2020). "Since most cases of BLS-type DLBCL are linked to an activated B-cell immunophenotype with expression of BCL-6 and MUM-1/IRF-4, we hypothesized that tumor progenitor cells are activated B cells that colonize the bone marrow before neoplastic transformation." (PMID 33288848, 2020). "Thus, the computational analysis highlights IRF4 as a potential active participant in mediating the anti-tumor effects observed." (PMID 32855526, 2020). "A myeloid cell-specific knockout of IRF4 increased the tumor weight in B16F10 tumor bearing mice." (PMID 32448983, 2020). "Finally, in order to confirm the axis of miR-99b-mTOR and/or κB-ras2 and miR-99b-mTOR/IRF4 in vivo, we detected the expression of κB-ras2, mTOR and IRF4 in TAMs sorted from tumor-bearing mice after delivery of saline, miR-99b, V&Ctrl and V&miR-99b." (PMID 32948650, 2020). "Tumor markers IRF4, SOX17, and MEF2C are all involved in the development of various tumors." (PMID 32420368, 2020). "We also compared the levels of the anti-apoptotic proteins, BCL2 and IRF4, in the two tumor types." (PMID 30125329, 2018). "In addition, the authors investigated the long-term fate of the mutant mice to show cooperative tumor suppressive functions for IRF4 and IRF8 in both myeloid and lymphoid cells." (PMID 22003407, 2011). "Given its role as a critical transcriptional regulator that limits pre-B cell expansion and promotes pre-B cell differentiation, it is reasonable to assume that IRF4 may function as a tumor suppressor against pre-B cell transformation." (PMID 21818355, 2011).
tumor (continued). "Moreover, we provided evidence that IRF4 functions as a classical tumor suppressor gene to inhibit c-Myc induced leukemogenesis." (PMID 21818355, 2011). "We did not observe a significant increase in tumor formation in IRF4 deficient mice, indicating that deficiency for IRF4 alone isn't sufficient for tumor development." (PMID 21818355, 2011). "Thus, IRF4 functions as a classical tumor suppressor to inhibit c-Myc induced B cell leukemia in EμMyc mice." (PMID 21818355, 2011). "Our finding is consistent with a previous study which shows that IRF4 functions as tumor suppressor in BCR/ABL oncogene induced B-ALL and further demonstrates that IRF4 is capable of functioning as a tumor suppressor against a broad spectrum of oncogene insults at the pre-B stage." (PMID 21818355, 2011). "Indeed, a previous study has shown that IRF4 functions as a tumor suppressor to inhibit BCR/ABL oncogene induced B cell acute lymphoblastic leukemia (B-ALL)." (PMID 21818355, 2011). "IRF4-deficient mice failed to mount antibody, cytotoxic, and anti-tumor responses." (PMID 40733503, 2025). "As B cells are central architects of TLSs, orchestrating their formation and maturation into germinal center-like structures, we hypothesized that IRF4 might regulate TLS development by modulating B cell differentiation or functional states within the tumor microenvironment." (PMID 40607252, 2025). "Collectively, we hypothesized that IRF4 might contribute to tumor progression in ccRCC." (PMID 40607252, 2025). "Consequently, we show that IRF4 controls the expression of tumour suppressor genes known to be silenced by these epigenetic modifications, for instance cyclin-dependent kinase inhibitors CDKN1A and CDKN1B, the PI3-AKT pathway regulator PTEN, and primary cilium components." (PMID 38880659, 2024). "IRF4 encodes a transcription factor important in regulating immune responses and has been shown to be overexpressed in NSCLC tumor tissue and may play a role in increasing cell proliferation rate and colony formation of NSCLC tumor cells through activation of the Notch-Akt signaling pathway." (PMID 38975340, 2024). "The cooperation of BATF and IRF4 could again exhaust tumor-infiltrating CAR T cells." (PMID 37231356, 2023). "Accordingly, IRF4 deficiency further favors the generation of MDSCs in the TME, and increases the expansion of M-MDSCs and the infiltration of PMN-MDSCs with a strong suppressive capacity, which inhibits the proliferation of CD8+ T cells through IL10 and ROS generation and promotes tumor growth." (PMID 36814912, 2023). "However, there was an amplification of IRF4 in the implanted tumour material, though diagnostic tumour material was not available to rule out its presence prior to relapse." (PMID 37357529, 2023). "Moreover, based on the overexpression of BATF and IRF4 in exhausted T cells, knockdown of BATF or IRF4 could remarkably enhance the tumor-killing ability of CAR-T cells by reversing their exhaustion and prolonging their persistence." (PMID 36814912, 2023). "Therefore, the Roquin-IRF4 axis may also serve as a potential target for enhancing anti-tumor immunity." (PMID 36814912, 2023). "Moreover, although we chose to knock down the expression levels of CKAP5 protein in this study, advancing this new therapeutic option to the clinic may require choosing a more tumor‐specific target such as Bcl‐2 or Irf‐4." (PMID 37171801, 2023). "Therefore, specifically targeting IRF4 in Treg cells may reverse the tumor microenvironment from immunosuppression to immune activation against tumor cells, which may become an effective anti-tumor therapeutic strategy." (PMID 36814912, 2023). "Notably, IRF4 can in turn activate the NF-κB signaling pathway in several tumor types." (PMID 36077849, 2022).
tumor (continued). "In our study, we found IRF4's expression was meaningfully high up in Immunity_H than in Immunity_M and Immunity_L; meanwhile, we verified the positive correlation between IRF4 and PD-L1 and demonstrated that IRF4 could enhance immunosuppressive effect of tumor microenvironment." (PMID 35983077, 2022). "Moreover, the subsets of MDSCs in KO tumor-bearing WT and IRF4 mice were also explored by FACS." (PMID 33708218, 2021). "In addition, metformin reduced the expression of several proteins related to immune responses, including VTCN1, a B7 family member involved in immune regulation, as well as IRF4, a regulator of lymphocyte growth and differentiation, leading to decreased tumor cell proliferation and metastasis." (PMID 33690729, 2021). "Considering that the IRF4 gene is localized on chromosome 6p, which is usually associated with a good prognosis, correlation of IRF4/MUM1 protein expression in primary UM and the tumour cell copy number variations may be of value for future use in diagnostic laboratories." (PMID 33008022, 2020). "In P4, an IRF4 mutation was detected in the LN tumor but not in the T or D tumor." (PMID 32929369, 2020). "Since Tax expression is a strong selective disadvantage during lymphomagenesis and is typically silenced, ATLL cells in the context of tumor immunity may be more sensitive to IRF4-targeted therapies than the same cells cultured ex vivo or as xenografts in immunodeficient mouse models." (PMID 32859220, 2020). "Moreover, the survival of tumor-bearing Irf4−/− mice was significantly reduced." (PMID 32448983, 2020). "Furthermore, knockdown of oncogenic IRF4 induced the tumor suppressive activities of IRF8." (PMID 23658517, 2013). "Collectively, these findings suggest that IRF4 fosters TLS immaturity by halting B cell development and impairing spatial organization, thereby contributing to an immunosuppressive tumor microenvironment and weakening anti-tumor immunity." (PMID 40607252, 2025). "In EBV-infected B-cells, IRF4 and BATF jointly repress tumor suppressors like PRDM1 and BCL2L11, thereby promoting transformation." (PMID 40313738, 2025). "Upon T‐cell activation, IRF4 up‐regulation modulates PD‐1 expression, reduces IFN‐γ production and diminishes the proliferative capacity of tumour‐infiltrating lymphocytes (TILs)." (PMID 40356050, 2025). "Recent efforts toward improving the efficacy and sustainability of anti-tumor immunotherapies include targeting the TME, which involves multiple transcription regulatory factors, including IRF4." (PMID 40733503, 2025). "This blocks key TFs (e.g., IRF4, MEF2C), lowers oncogene expression (e.g., MYC, IRF4), and slows tumor cell proliferation, while minimizing risks to normal SE function." (PMID 40895527, 2025). "CRC cells secreted TIMP1 into the tumor microenvironment, where it induced M2-like macrophage polarization and increased the expression of immunosuppressive mediators such as CSF1 and IRF4." (PMID 41511313, 2025). "Thus, it remains unclear how to optimally leverage the activity of IRF4 in anti-tumour T cells." (PMID 39399500, 2024). "Integrative transcriptomic and epigenomics data showed that IRF4, alone or in combination with BATF, was directly responsible for tumor immunosuppression." (PMID 38918817, 2024). "Studies have shown that IRF4 regulates the function of TAM and is involved in tumor progression and metastasis." (PMID 39123188, 2024). "Collectively, the deletion of IRF4 in Pmel-1 ACT, starting at 20 days after tumor implantation, markedly impairs tumor control, which correlates with reduced frequency and function of Pmel-1 TILs." (PMID 38178902, 2023).